CCT4 (chaperonin containing TCP1 subunit 4)
Description:
Component of the chaperonin-containing T-complex (TRiC), a molecular chaperone complex that assists the folding of actin, tubulin and other proteins upon ATP hydrolysis. The TRiC complex mediates the folding of WRAP53/TCAB1, thereby regulating telomere maintenance. As part of the TRiC complex may play a role in the assembly of BBSome, a complex involved in ciliogenesis regulating transports vesicles to the cilia.
Synonyms: CCTD; SRB; CCT-DELTA
Tractability: Small molecule: a structure with a bound ligand is known. PROTAC: ubiquitination databases record sites on it; its protein half-life has been measured.
Target class: Enzyme; Hydrolase
Gene: Protein-coding gene on chromosome 2 (61,868,085 to 61,888,696, reverse strand). Ensembl gene ENSG00000115484.
Subcellular location: Cytoplasm; Melanosome; Cytoplasm, cytoskeleton, microtubule organizing center, centrosome; Cytoplasm, cytoskeleton, cilium basal body
Subcellular location (Human Protein Atlas): Cytosol; Nucleoplasm
Pathways (Reactome):
Metabolism of proteins: Association of TriC/CCT with target proteins during biosynthesis; Cooperation of PDCL (PhLP1) and TRiC/CCT in G-protein beta folding; Folding of actin by CCT/TriC; Formation of tubulin folding intermediates by CCT/TriC; Prefoldin mediated transfer of substrate to CCT/TriC
Organelle biogenesis and maintenance: BBSome-mediated cargo-targeting to cilium
Gene Ontology:
Molecular function: ATP hydrolysis activity; protein binding; protein folding chaperone; RNA binding; ATP binding; ATP-dependent protein folding chaperone
Biological process: positive regulation of protein localization to Cajal body; positive regulation of telomerase RNA localization to Cajal body; positive regulation of telomere maintenance via telomerase; protein folding; protein stabilization; scaRNA localization to Cajal body
Cellular component: centrosome; chaperonin-containing T-complex; cytoplasm; cytosol; extracellular exosome; melanosome; microtubule; cell body; zona pellucida receptor complex
Genetic constraint (gnomAD): Loss-of-function variants: 7 observed, 20.31 expected, observed/expected ratio (o/e) 0.34, 90% interval 0.19 to 0.65. The upper end of that interval is the gene's LOEUF score, 0.65, which puts it in group 2 of 6, group 1 being the genes least tolerant of losing a copy. Missense variants: 284 observed, 335.44 expected, observed/expected ratio (o/e) 0.85, 90% interval 0.77 to 0.93. Synonymous variants: 122 observed, 121.41 expected, observed/expected ratio (o/e) 1, 90% interval 0.87 to 1.17.
Homologues: Orthologues: chimpanzee CCT4 (99% identical), rabbit CCT4 (99% identical), dog CCT4 (98% identical), guinea pig CCT4 (98% identical), pig CCT4 (98% identical), rat Cct4 (97% identical), mouse Cct4 (97% identical), macaque CCT4 (91% identical), tropical clawed frog cct4 (90% identical), zebrafish cct4 (87% identical), Drosophila melanogaster CCT4 (68% identical), Caenorhabditis elegans cct-4 (63% identical). Paralogues in human: CCT5 (37% identical), CCT7 (32% identical), CCT3 (32% identical), TCP1 (31% identical), CCT2 (30% identical), CCT8 (27% identical), CCT6B (27% identical), CCT6A (27% identical), PIKFYVE (24% identical), CCT8L2 (22% identical), BBS12 (18% identical), MKKS (18% identical), and 1 more.
Diseases named in the same sentence as CCT4 in open-access papers:
CCT4 is named in the same sentence as 54 diseases in open-access papers, as found by Europe PMC text mining. Sharing a sentence is not in itself a finding about the gene and the disease. The quoted sentences say what the papers report.
glioblastoma (7 papers, 2020 to 2025). The most malignant astrocytic tumor (WHO grade IV). "Several researches have revealed that CCT4 expression level was associated with the prognostic of glioblastoma multiforme and ovarian cancer." (PMID 33897772, 2021). "For instance, YBX1 has been shown to bind to the 5′-UTR of CCT4 mRNA and promote its translation, thereby facilitating glioblastoma development through mLST8 folding and activation of the mTOR signaling pathway." (PMID 40819060, 2025). "In patients with glioblastoma, high protein expression of YB-1 correlated with increased expression of CCT4 and mLST8 and activated mTOR signaling." (PMID 35239512, 2022). "Taken together, our results show that we have identified the YB-1/CCT4/mLST8/mTOR axis as a contributor to glioblastoma growth and suggest a therapeutic approach to target this axis using competitive RNA oligonucleotides." (PMID 35239512, 2022). "Taken together, these findings uncover a disrupted proteostasis pathway involving a YB-1/CCT4/mLST8/mTOR axis in promoting glioblastoma growth, suggesting that YB-1 is a potential therapeutic target for the treatment of glioblastoma." (PMID 35239512, 2022). "In glioma, YBX1 may act as an important activator of the mTOR signaling pathway and mediate the YBX1/CCT4/mLST8/mTOR axis to promote the growth of glioblastomas." (PMID 38849679, 2024). "CCT4 may facilitate glioblastoma cell growth by involving the YB-1/CCT4/mLST8/mTOR signaling pathway." (PMID 37006287, 2023). "Upregulation of CCT4 in glioblastoma may increase the recognition of certain substrates and accelerate conformational changes during the folding process." (PMID 35239512, 2022). "YB-1 maintains the self-renewal of glioblastoma stem–like cells via the CCT4/mLST8 cascade." (PMID 35239512, 2022). "The YB-1/CCT4/mLST8/mTOR axis promotes glioblastoma growth in vivo." (PMID 35239512, 2022). "The YB-1/CCT4/mLST8/mTOR pathway is upregulated in patients with glioblastoma." (PMID 35239512, 2022). "CCT4 participates in protein CCT6A as a potential prognostic biomarker in glioblastoma." (PMID 33313411, 2020). "Next, we surveyed the expression of YB-1, CCT4, mLST8, and phospho-S6K1 (T389) using a cohort of glioblastoma patient samples by performing IHC assays." (PMID 35239512, 2022). "Moreover, higher levels of CCT4, mLST8, and activated S6K1 predicted a poor survival, similarly to YB-1, implying that YB-1 may serve as a promising target for the treatment of glioblastoma." (PMID 35239512, 2022).
breast carcinoma (6 papers, 2021 to 2025). "A systematic analysis of protein half-lives in MCF-7 breast cancer cells found, in contrast, that CCT4 had the longest half-life (∼10.6 h), followed by CCT8, CCT7 and CCT2, with half-lives between 7–8 h, and CCT5 and CCT3 with the shortest half-lives of 4.6 and 2.5 h, respectively." (PMID 35602608, 2022). "Clinically, elevated CCT4 levels tended to correlate with advanced disease and worse patient survival in LUAD, aligning with observations in other malignancies such as breast cancer." (PMID 41403933, 2025). "For example, CCT2, CCT3, CCT4, and CCT5 were increased in breast cancer cells and positively correlated with tumor progression." (PMID 40374617, 2025). "Pulse-chase experiments with mammary carcinoma FM3A cells revealed that turnover rates of individual CCT subunits varied significantly, with CCT4 having the shortest half-life (∼4 h) and CCT2 the longest half-life (∼8 h)." (PMID 35602608, 2022). "NUDCD1, ENY2, PNO1, CCT4 and PSMD14 are considered to promote the proliferation, invasion and treatment resistance of tumor cells in a variety of cancers, including pancreatic cancer, rectal cancer, liver cancer, breast cancer, glial cancer and head and neck squamous cell carcinoma." (PMID 37827692, 2023).
lung carcinoma (5 papers, 2016 to 2023). "Amplification of CCT4 gene were detected in clinical lung cancer cases and associated with decreased survival." (PMID 31537905, 2020). "Previously, it was indicated that LAYN, CCT4, CTHRC1, and FHL1 gene were correlated with the migrational potential of lung cancer cells." (PMID 27586393, 2016). "The in vitro siRNA-mediated MALAT1 silencing resulted in impaired lung cancer cell motility by altering the expression levels of cell motility-related genes, such as HMMR at pre-mRNA transcriptional level and CTHRC1, CCT4 and ROD1 at post-transcriptional level." (PMID 28253859, 2017).
Sensory neuropathy (5 papers, 2008 to 2026). Peripheral neuropathy affecting the sensory nerves. "CCT4 has also been linked to neurological diseases: a mutation in CCT4/5 subunits causes sensory neuropathy, and CCT4 expression is upregulated in AD." (PMID 41104595, 2026). "A mutation in cct2 has been found in a family with Leber congenital ameurosis retinal phenotype and mutations in cct4 and cct5 have been related to sensory neuropathy." (PMID 30777146, 2019). "Mutated CCT4/5 subunits cause sensory neuropathy and CCT5 expression is decreased in Alzheimer's disease." (PMID 27929117, 2016). "Chaperonin subunit 4 (cct4) involved in folding tubulin and other cytosolic proteins is included, since mutation of this protein leads to early onset sensory neuropathy." (PMID 18366630, 2008).
hepatocellular carcinoma (3 papers, 2023 to 2025). A malignant tumor that arises from hepatocytes. "One report identified upregulation of TRAPPC5 in hepatocellular carcinoma (HCC) subsequent to knockout of CCT4, a key component of HCC glycolytic metabolism." (PMID 39769094, 2024). "For example, there is a significant difference in the expression of TCP1/CCT2/CCT3/CCT4/CCT5/CCT6A/CCT7/CCT8 in hepatocellular carcinoma." (PMID 37058032, 2023). "Prior work in hepatocellular carcinoma (HCC) demonstrated that CCT4 physically interacts with Cdc20, a key activator of APC/C, and this interaction promotes the disassembly of the mitotic checkpoint complex (MCC) to activate APC/C." (PMID 41403933, 2025).
lung adenocarcinoma (3 papers, 2021 to 2025). A carcinoma that arises from the lung and is characterized by the presence of malignant glandular epithelial cells. "In addition, downregulation of CCT4 can significantly inhibit the migration of lung adenocarcinoma cells." (PMID 35836576, 2022). "MALAT-1 enhanced cell motility of lung adenocarcinoma by downregulating CCT4." (PMID 33815471, 2021).
melanoma (3 papers, 2017 to 2021). A malignant, usually aggressive tumor composed of atypical, neoplastic melanocytes. "First, we can conclude that our MS approach allows detection of three HLA-A2 restricted neoepitopes presented on the melanoma cells (AGPS, ENC1, CCT4)." (PMID 31921104, 2019). "Interestingly, this TGF-β activity also correlated with expression of an experimentally validated 6-gene “metagene” (VAV2, CORO1A, EPB41L1, CCT4, FRAP1, GJB3) reflecting integrin β1 activity, further supporting a link between integrin activity and TGF-β activity in human melanoma." (PMID 28448494, 2017).
ovarian carcinoma (3 papers, 2021 to 2024). A malignant neoplasm originating from the surface ovarian epithelium. "Aside from that, CCT4 up-regulation and PRAME mutations was correlated with a good prognosis for ovarian cancer patients." (PMID 37835834, 2023). "Notably, a study has analyzed 21 ovarian cancer‐associated CTAs and found that GAGE2, CT45, CCT4, and PRAME cancer/testis antigens were revealed to be correlated with the prognosis for ovarian cancer patients." (PMID 38896069, 2024). "The CCT4 up-regulation and PRAME mutations were correlated with a good prognosis for ovarian cancer, while higher levels of GAGE2A and CT45A1 mRNAs were correlated with a poor prognosis for ovarian cancer patients." (PMID 37835834, 2023). "Thus, disease-free survival was significantly higher in the group of patients with increased expression of the CCT4 gene in the ovarian cancer samples (p-value = 0.013, n = 367)." (PMID 37835834, 2023). "Among the 21 selected CTAs, GAGE2, CT45, CCT4, and PRAME cancer/testis antigens were revealed to be correlated with the prognosis for ovarian cancer patients, and GAGE2, CCT4, and PRAME were identified for the first time." (PMID 37835834, 2023). "Thus, GAGE2, CT45, CCT4, and PRAME cancer/testis antigens can be considered as new potential prognostic markers for ovarian cancer disease and need to be further investigated." (PMID 37835834, 2023). "Thus, GAGE2, CT45, CCT4, and PRAME cancer/testis antigens can be considered as potential prognostic markers for ovarian tumors, and GAGE2, CCT4, and PRAME were revealed to be correlated with the prognosis for ovarian cancer patients for the first time." (PMID 37835834, 2023).
acute myelogenous leukemia (2 papers, 2020 to 2022). "Instead, NPM1, which is involved in non-Hodgkin lymphoma and acute myelogenous leukemia, and CCTs (CCT4, CCT5, and CCT7) were up-regulated." (PMID 35464471, 2022).
diabetes (2 papers, 2012 to 2018). "Our results indicate that of 89 ER stress genes, the expression of 12 genes in the retinas of diabetic rats was downregulated by the third month of diabetes development, and the expression of CCT4 increased within the first month." (PMID 21904541, 2012).
glioma (2 papers, 2022 to 2024). A benign or malignant brain and spinal cord tumor that arises from glial cells (astrocytes, oligodendrocytes, ependymal cells). "We applied the GSC model to obtain a deeper understanding of the role of the YB-1/CCT4/mLST8/mTOR axis in glioma growth." (PMID 35239512, 2022).
hereditary sensory neuropathies (2 papers, 2021 to 2023). "Interestingly, mutations in the TRiC subunits CCT4 and CCT5 are associated with hereditary sensory neuropathies implicating that dysfunction of TRiC in axons from lyso-Gb3 exposure could be a contributor to the peripheral neuropathy observed in FD." (PMID 37145097, 2023).
retinal degeneration (2 papers, 2019 to 2023). Degeneration of the retina. "Accordingly, retinal degeneration within cct4-deficient mutants, with only a rudimentary lens and clustered pigment remaining, was confirmed at six dpf in this study." (PMID 36937198, 2023). "Similar to our cct5 mutant, cct1, cct2, cct3, cct4 and cct8 mutant zebrafish show retinal degeneration, suggesting that the cct5/tcf7l1a double mutant phenotype is due to abrogation of TRiC chaperonin function, a conclusion supported by cct3 knockdown in tcf7l1a mutants." (PMID 30777146, 2019).
acute kidney injury (1 paper, 2023). Sudden and sustained deterioration of the kidney function characterized by decreased glomerular filtration rate, increased serum creatinine or oliguria. "Five genes (CCT4, HSP90AA1, NCL, PABPC1, YBX1) were found to be associated with kidney disease, acute kidney injury, edema, tumor metastasis, transitional cell carcinoma, necrosis, and inflammation." (PMID 37058032, 2023). "CCT4, HSP90AA1, NCL, PABPC1, and YBX1 were found to be associated with kidney disease, acute kidney injury, edema, tumor metastasis, transitional cell carcinoma, necrosis, and inflammation." (PMID 37058032, 2023).
B-cell neoplasm (1 paper, 2025). A group of heterogeneous lymphoid tumors generally expressing one or more B-cell antigens or representing malignant transformations of B-lymphocytes. "CCT4 exhibited diverse genomic alterations, with the highest alteration rates observed in mature B-cell neoplasm, endometrial cancer, and NSCLC, primarily driven by gene amplification and mutations." (PMID 41403933, 2025).
chronic lymphocytic leukemia (1 paper, 2015). "Except CCT4 gene which was also mapped to 2p as REL, these DEGs were not overlapping with those associated with 2p gain in chronic lymphocytic leukemia." (PMID 26324762, 2015).
COVID-19 (1 paper, 2025). A disease caused by infection with severe acute respiratory syndrome coronavirus 2. "Remarkably, telomere maintenance processes were observed to be one of the top biological processes activated in patients with mild COVID-19 via activation of genes such as CCT2, CCT3, CCT4, CCT5 and CCT6A." (PMID 41141600, 2025).
diabetic kidney disease (1 paper, 2023). Progressive kidney disorder caused by vascular damage to the glomerular capillaries, in patients with diabetes mellitus. "However, notably, diabetic kidney disease markers, such as CCT4 and CNDP2, were more abundant in glomeruli from PTDM patients than in those from T2DM patients." (PMID 37626301, 2023).
esophageal squamous cell carcinoma (1 paper, 2024). Esophageal squamous cell carcinoma (ESCC) is a type of esophageal carcinoma (EC) that can affect any part of the esophagus, but is usually located in the upper or middle third. "For instance, CCT4 (chaperonin containing TCP-1) knockdown has been shown to enhance the sensitivity of cisplatin in esophageal squamous cell carcinoma." (PMID 39681067, 2024).
Nephroblastoma (1 paper, 2023). An embryonal neoplasm characterized by the presence of epithelial, mesenchymal, and blastema components. "Although CCT4 is abnormally expressed in various tumors and regulates multiple cancer-related genes, its expression, and role in nephroblastoma are still unclear." (PMID 37058032, 2023). "CCT4 might play an essential role in the occurrence and development of Wilms tumor, and they may participate in the occurrence and development of Wilms tumor through the ERBB signal pathway." (PMID 37058032, 2023). "Typical data sets were used to verify the significant role of CCT4 in nephroblastoma." (PMID 37058032, 2023). "The main result of this study is that the expression of CCT4 is low in nephroblastoma." (PMID 37058032, 2023). "chaperonin containing TCP-1 subunit 4 (CCT4) was downregulated in tumor tissue samples, which may have reverse regulatory significance for Wilms tumor." (PMID 37058032, 2023). "CCT4 may be involved in the cell cycle, promote apoptosis, and may be involved in the occurrence and development of nephroblastoma through the ERBB signal pathway." (PMID 37058032, 2023). "In conclusion, this study used bioinformatics methods to examine the data from a large number of nephroblastoma samples and discovered that CCT family genes, particularly CCT4, play a crucial role in the occurrence and progression of nephroblastoma and may do so via the ERBB signal pathway." (PMID 37058032, 2023). "In this study, no clinical samples were tested to verify the function of CCT4 in nephroblastoma further." (PMID 37058032, 2023). "We found that core genes (CCT4, HSP90AA1, NCL, PABPC1, YBX1) were lowly expressed in tumor tissue samples and highly expressed in standard tissue samples, which may have reverse regulatory significance for Wilms tumor." (PMID 37058032, 2023).
osteosarcoma (1 paper, 2025). A usually aggressive malignant bone-forming mesenchymal neoplasm, predominantly affecting adolescents and young adults. "In osteosarcoma models, CCT4 was found to be indispensable for cancer cell survival: CRISPR/Cas9 knockout of CCT4 was lethal to osteosarcoma cells, and even partial knockdown significantly impaired their clonogenic growth and invasion." (PMID 41403933, 2025).
type 2 diabetes (1 paper, 2023). "A PCA plot bar graph based on the expression levels of MAFA, NKX6.1, CCT4, XBP1 and GRP78, as well as PDIA1, shows a clearer division between the three groups, highlighting the progression from NGT to IGT and then type 2 diabetes." (PMID 36280617, 2023).